RN7SKP46 (RN7SK pseudogene 46)
Gene: Miscellaneous RNA gene on chromosome 3 (157,930,492 to 157,930,725, reverse strand). Ensembl gene ENSG00000251751.
Homologues: Orthologues: chimpanzee 7SK (99% identical), guinea pig 7SK (40% identical), mouse Gm54723 (35% identical). Paralogues in human: RN7SKP176 (64% identical), RN7SKP44 (64% identical), RN7SKP50 (64% identical), RN7SKP9 (64% identical), RN7SKP217 (64% identical), RN7SKP269 (64% identical), 7SK (63% identical), RN7SKP4 (63% identical), RN7SKP133 (62% identical), RN7SKP255 (62% identical), RN7SKP1 (62% identical), RN7SKP118 (62% identical), and 284 more.